DDR1 (discoidin domain receptor tyrosine kinase 1)
Diseases named in the same sentence as DDR1 in open-access papers (continued):
Sharing a sentence is not in itself a finding about the gene and the disease.
mesothelioma (4 papers, 2016 to 2023). A usually malignant and aggressive neoplasm of the mesothelium which is often associated with exposure to asbestos. "Overall, our data suggest that IGF-I/IGF-IR system triggers stimulatory actions through both GPER and DDR1 in aggressive tumors as mesothelioma and lung tumors." (PMID 27384677, 2016). "Eventually, we went the extra mile to investigate the survival curves of 33 TCGA cancer types using GEPIA database, revealing DDR1 expression to be significantly correlated with DFS in CHOL and KICH, OS in mesothelioma (MESO), and both OS and DFS in KIRC." (PMID 35935941, 2022). "Similarly, the analysis of the KM OS revealed that DDR1 acts as a protective factor for patients with KIRC, mesothelioma (MESO), and uveal melanoma (UVM)." (PMID 37031216, 2023).
myeloid leukemia (4 papers, 2014 to 2022). A clonal proliferation of myeloid cells and their precursors in the bone marrow, peripheral blood, and spleen. "Taken together, for the first time, we demonstrate that remodeled collagen IV is a potent activator of DDR1 and AKT that also modulates both migration and adhesion of myeloid leukemia cells." (PMID 24519883, 2014). "Collagen IV could also activate DDR1 and AKT to promote invasion and migration of myeloid leukemia cells." (PMID 31315643, 2019). "Moreover, DDR1 therapeutic targeting in vivo was not yet characterized for the treatment of myeloid leukemia." (PMID 35559262, 2022).
Nephropathy (4 papers, 2016 to 2023). A nonspecific term referring to disease or damage of the kidneys. "Expression of DDR1 on macrophages seems to promote MCP1-induced cell migration, suggesting that DDR1 contributes to kidney damage by directly promoting inflammatory responses." (PMID 36249782, 2022). "In hereditary angiopathy with nephropathy, aneurysms, and muscle cramps syndrome DDR1 was shown to be upregulated in parietal epithelial cells by immunostaining, while in the remnant kidney model DDR1 is upregulated in glomeruli." (PMID 36249782, 2022). "Captopril was more efficient in improving renal function due to the fact that Captopril administration started before disease initiation (preventive approach), whilst the DDR1 inhibitor was only administered during the progression of nephropathy (curative or interventional approach)." (PMID 29859097, 2018). "Here, we have shown that in severe models of renal disease, pharmaco-genetic inhibition of DDR1 expression by antisense administration can arrest the progression of nephropathy, providing thus for the first time a proof of concept of a treatment based on DDR1 blockade." (PMID 26880216, 2016). "CUBN-rs1801239 and DDR1-rs116772905 were associated with all the UACR-derived phenotypes, in both the overall and non-diabetic cohorts, but not with kidney damage." (PMID 37446387, 2023). "CUBN-rs1801239 and DDR1-rs116772905 were associated with all the UACR-derived phenotypes, (along with SHROOM3-rs17319721 and ALLC-rs12615970, except for macroalbuminuria) at least in the overall and non-diabetic cohorts, but not with kidney damage." (PMID 37446387, 2023).
oral squamous cell carcinoma (4 papers, 2019 to 2024). "Previously, we identified an elevated expression of DDR1 in oral squamous cell carcinoma (OSCC) cells." (PMID 32244515, 2020). "However, the precise mechanisms underlying the abnormal expression of DDR1 in oral squamous cell carcinoma (OSCC) has not been well investigated." (PMID 31253192, 2019).
pancreatic adenocarcinoma (4 papers, 2013 to 2023). "The interaction between COLXV with both DDR1 and E-Cad was confirmed in a second pancreatic adenocarcinoma cell line, S2-013." (PMID 23991074, 2013). "As an example, intact COLα1 (I) was shown to promote DDR1 degradation in a mouse pancreatic adenocarcinoma cell line, whereas a COLα1 (I) fragment (from the N-terminus until and including Gly775) produced following MMP-8 cleavage, was found to activate the DDR receptor." (PMID 37373151, 2023).
schwannoma (4 papers, 2023 to 2026). A benign, usually encapsulated slow growing tumor composed of Schwann cells. "Moreover, mutations in DDR1 were found to be associated with 11% of Schwannoma-cell tumors in a recent study of a large series of patients with Schwannoma." (PMID 36675255, 2023). "Other recurrently altered genes reported in schwannomas include LATS1, LATS2, ARID1A, ARID1B and DDR1." (PMID 41300852, 2025).
uveal melanoma (4 papers, 2021 to 2025). A melanoma derived from melanocytes of the uveal tract. "Discordin domain receptor tyrosine kinase 1 (DDR1) has also been implicated in MCL1 expression in uveal melanoma, where the downregulation of DDR1 also decreases MCL1 expression." (PMID 34831420, 2021). "In uveal melanoma (UVM), RB, and LUAD, high DDR1 expression is associated with reduced apoptotic signaling (r = −0.33) and suppressed DNA damage and repair responses (r = −0.43 and −0.49, respectively)." (PMID 40869052, 2025). "Activation of DDR1/STAT3 signaling pathway by extracellular matrix remodeling promotes liver metastatic colonization (e.g., survival, outgrowth and stemness of cancer cells in the metastatic site) in uveal melanoma." (PMID 37709489, 2023).
bladder tumor (3 papers, 2019 to 2022). "For instance, it promotes collective cell migration independent of binding to collagen while collagen-induced DDR1 signaling is required for bladder tumor cells colonization of the lung." (PMID 35309920, 2022).
glomerulosclerosis (3 papers, 2016 to 2024). A hardening of the kidney glomerulus caused by scarring of the blood vessels. "In multiple preclinical studies DDR1 has been shown to play a major role in the pathogenesis of fibrosis and glomerulosclerosis." (PMID 29859097, 2018). "We then aimed to assess the effect of DDR1 inhibition in the context of progressive glomerulosclerosis in the NEP25 mouse model." (PMID 29859097, 2018). "Thus, in a model of angiotensin II-induced hypertensive nephropathy, DDR1 null mice were protected against proteinuria, perivascular and periglomerular inflammation, glomerulosclerosis and interstitial fibrosis." (PMID 26880216, 2016).
head and neck squamous cell carcinoma (3 papers, 2025 to 2026). A squamous cell carcinoma that arises from any of the following anatomic sites: lip and oral cavity, nasal cavity, paranasal sinuses, pharynx, larynx, and salivary glands. "Analysis of data from The Cancer Genome Atlas-head and neck squamous cell carcinoma (TCGA-HNSC) dataset revealed a striking upregulation of DDR1 in tumor tissues compared to normal tissues." (PMID 40993737, 2025).
Hodgkins lymphoma (3 papers, 2015 to 2025). A heterogeneous group of malignant lymphoid neoplasms of B-cell origin characterized histologically by the presence of Hodgkin and Reed-Sternberg (HRS) cells in the vast majority of cases. "Previously, we showed that DDR1 is overexpressed in Hodgkin lymphoma and that DDR1 activation by collagen enhanced the survival of B‐cell lymphoma lines." (PMID 40401507, 2025). "A high expression of DDR1 in Hodgkin lymphoma cells provides a protective shield against apoptosis, a process that typically occurs in Reed–Sternberg and normal Hodgkin cells." (PMID 37627077, 2023). "Short-term exposure to collagen is sufficient to significantly decrease the survival of DG75 EBV-negative Burkitt lymphoma cells or L428 Hodgkin lymphoma cells via up-regulation of DDR1." (PMID 26527314, 2015).
Hyperinsulinemia (3 papers, 2016 to 2024). An increased concentration of insulin in the blood. "In addition, the potential anti-cancer effect of DDR1 ablation in animal models mimicking hyperinsulinemia needs to be tested." (PMID 37461077, 2023). "The correlation between DDR1 and IR and the finding that insulin may also upregulate DDR1, raise the possibility that insulin resistance and compensatory hyperinsulinemia may enhance DDR1 in neoplastic tissues." (PMID 26655502, 2016).
Hypertension (3 papers, 2021 to 2022). The presence of chronic increased pressure in the systemic arterial system. "Loss of DDR1 attenuates fibrosis in a mouse model of kidney injury induced by hypertension or partial renal ablation as well as in the Alport mouse model." (PMID 34941574, 2022). "In hypertension-induced nephropathy, immunostaining revealed DDR1 upregulation in renal vessels and in glomeruli, while in the unilateral ureteral obstruction (UUO) model, increased DDR1 expression is detected in the interstitium." (PMID 36249782, 2022).
lupus nephritis (3 papers, 2017 to 2021). Glomerulonephritis in the context of systemic lupus erythematosus. "SYK, BTK, PDGFR, EFGR, DDR1 and Janus kinase are implicated in the pathogenesis of lupus nephritis." (PMID 28391340, 2017). "To define more precisely the profile of DDR1 expression during the sequence of morphological changes observed in crescent formation, we performed IHC on lupus nephritis class IV-G (A/C) biopsies." (PMID 29859097, 2018). "DDR1 expression is increased in the glomeruli of patients with lupus nephritis." (PMID 34602056, 2021).
lymph node metastasis (3 papers, 2017 to 2023). "Further clinical analysis showed that high expression of DDR1 was statistically associated with lymph node metastasis, perineural invasion and lymphangiogenesis (p < 0.05)." (PMID 31253192, 2019). "When DDR1 expression was correlated with available clinicopathologic parameters, this revealed that higher expression levels were evident in higher-grade, higher-stage tumors and significantly correlated to the presence of lymph node metastasis." (PMID 37271822, 2023). "Further clinical analysis showed that high expression of DDR1 was statistically associated with lymph node metastasis, TNM stage and distant metastasis (P < 0.05) but not with age and differentiation (P > 0.05)." (PMID 28743276, 2017).
lymphoma (3 papers, 2019 to 2025). A malignant (clonal) proliferation of B- lymphocytes or T- lymphocytes which involves the lymph nodes, bone marrow and/or extranodal sites. "This suggests that USP7 may play a critical role in regulating DDR1 expression and could potentially serve as a prognostic biomarker in lymphomas." (PMID 40713963, 2025).
metastatic colorectal cancer (3 papers, 2018 to 2025). "DDR1 expression is associated with decreased OS in patients with metastatic colorectal cancer, and DDR1 phosphorylation is strongly increased in the corresponding metastatic lesions, indicating that COL4A6 promotes cell invasion via the E2F1/DDR1/FAK axis." (PMID 40603853, 2025).
multiple myeloma (3 papers, 2017 to 2022). "DDR1, a collagen tyrosine kinase, is downregulated by miR-199a-5p, which decreases multiple myeloma cell invasiveness." (PMID 29137361, 2017).
Ureteral obstruction (3 papers, 2016 to 2022). Obstruction of the flow of urine through the ureter. "However, the observed staining of DDR1 in the kidney following NTS administration or ureteral obstruction does not appear to be in T lymphocytes." (PMID 26880216, 2016).
acute kidney injury (2 papers, 2022). Sudden and sustained deterioration of the kidney function characterized by decreased glomerular filtration rate, increased serum creatinine or oliguria. "DDR1 deficient Col4a3-/- mice were reported to be protected from proteinuria and renal failure, suggesting DDR1 as an amenable therapeutic target." (PMID 35547199, 2022).
adenoma (2 papers, 2023 to 2024). A neoplasm arising from the epithelium. "In conclusion, DDR1 overexpression is a frequent feature in CRC as well as CR adenoma." (PMID 37271822, 2023). "First, to validate the correlation between DDR1 and MMDR in clinical cases, we compared the expression of DDR1 in normal colorectal tissue, adenomas, malignant primary CRC lesions and metastatic lesions." (PMID 38953306, 2024). "DDR1 overexpression is a frequent feature in CRC and CR adenoma." (PMID 37271822, 2023). "Forty-eight cases of CRC, 20 of CR adenoma, and 8 cases of non-tumoral colonic tissue were subjected to immunohistochemistry by DDR1 and β-catenin antibodies." (PMID 37271822, 2023).
B cell lymphoma (2 papers, 2016 to 2025). "CENPE expression was also downregulated following DDR1 activation in two B‐cell lymphoma lines and was lost in most DDR1‐expressing primary tumours." (PMID 40401507, 2025). "We validated the differential expression of a subset of DDR1 targets in both DDR1‐expressing GC B cells and B‐cell lymphoma lines using RT‐qPCR." (PMID 40401507, 2025). "We validated an antibody specific for CENPE protein and used this to show that CENPE protein levels were decreased by collagen treatment of the DDR1‐expressing B‐cell lymphoma lines and by expression of a constitutively activated DDR1 construct." (PMID 40401507, 2025). "We used RT‐qPCR to confirm the decreased expression of CENPE mRNA in collagen‐treated DDR1‐expressing GC B cells and B‐cell lymphoma lines." (PMID 40401507, 2025). "The kinesin motor protein, CENPE, was downregulated following DDR1 activation in both untransformed GC B cells and B‐cell lymphoma lines." (PMID 40401507, 2025). "This DDR1 tyrosine phosphorylation kinetic is consistent with that observed with cells growing in suspension such as K562 and B cell lymphoma." (PMID 27391444, 2016).
brain cancer (2 papers, 2014 to 2022). A primary or metastatic malignant neoplasm affecting the brain. "Although DDR1 is expressed in many normal tissues, upregulated expression of DDR1 in a variety of human cancers such as lung, colon and brain cancers is known to be associated with poor prognosis." (PMID 25369402, 2014).
chronic lymphocytic leukemia (2 papers, 2021 to 2023). "This elevated DDR1 expression is significantly associated with the ZAP70 gene, which is a well-known prognostic marker in chronic lymphocytic leukemia." (PMID 37627077, 2023).
colitis (2 papers, 2022 to 2025). Inflammation of the colon. "DDR1 deficiency attenuates intestinal mucosal barrier damage induced by dextran sulfate sodium (DSS)-induced colitis and reduces pro-inflammatory cytokine production." (PMID 39940867, 2025). "The involvement of DDR1 in the pathogenesis of colitis by mediating intestinal mucosal barrier damage in UC has been demonstrated, making DDR1 a novel target for the treatment of intestinal inflammation." (PMID 39940867, 2025). "For instance, a team led by Mingyue Zheng at SIOPA, Chinese Academy of Sciences, designed a novel DDR1 inhibitor that exhibited favorable oral therapeutic effects in DSS-induced colitis models in mice and effectively reduced inflammation." (PMID 39940867, 2025). "Research on DDR1 inhibitors for colitis treatment has focused on their anti-inflammatory effects and their role in protecting the intestinal mucosal barrier; numerous molecules have demonstrated therapeutic efficacy in preclinical studies." (PMID 39940867, 2025). "In vivo inhibition of DDR1 expression has demonstrated significant therapeutic protection against DSS-induced colitis." (PMID 39940867, 2025). "In a dextran sulphate sodium prompted animal colitis model, compound 191 potently reduced the production of pro-inflammatory cytokines and DDR1 auto phosphorylation in cells." (PMID 36557840, 2022). "Compound 191 inhibited pro-inflammatory cytokines and autophosphorylation of DDR1 in cells in a mouse colitis model induced by dextran sulfate sodium (DSS)." (PMID 36557840, 2022).
COVID-19 (2 papers, 2021 to 2022). A disease caused by infection with severe acute respiratory syndrome coronavirus 2. "Another innate immune polymorphism related to the development of COVID-19 is discoidin domain receptor 1 (DDR1) rs4618569." (PMID 35062298, 2022). "We focused on cytokine polymorphisms at rs12979860 and rs17047200 loci, the allele frequencies reported in previous literatures and DDR1 gene polymorphism in COVID-19 positive patients to explore their relation to coronavirus infection severity and mortality." (PMID 34071309, 2021). "From these data, it appears that the AA genotype of the rs4618569 variant of the DDR1 gene had a higher incidence of COVID-19 compared to the healthy control group (p = 0.026)." (PMID 34071309, 2021). "The C and A alleles of SNPs IFN-λ rs12979860, TLL1 rs17047200 correlate with the severity of COVID-19, where the AG genotype of the DDR1 rs4618569 variant are associated with severe COVID-19 cases and poor outcomes." (PMID 34071309, 2021). "Concerning the AA genotype of the DDR1 rs4618569 variant, it is more likely to be found in COVID-19 patients versus healthy controls, with p = 5.422." (PMID 34071309, 2021). "The CC genotype of rs12979860 cytokine, the AA genotype of TLL1 rs17047200 and the AA genotype of the rs4618569 variant of DDR1 showed a higher incidence of COVID-19 compared to the others." (PMID 34071309, 2021). "Patients containing DDR1 rs4618569 had high C reactive protein (CRP), D-dimer, ferritin, high risk of mechanical ventilation, as well as severe COVID-19 and an increase in the mortality rate." (PMID 35062298, 2022). "Methods: 141 COVID-19 positive patients and 100 healthy controls were tested for interferon-lambda-3 rs12979860, TLL1 rs17047200 and DDR1 rs4618569 polymorphism by TaqMan probe-based genotyping." (PMID 34071309, 2021).
cyst (2 papers, 2019). A sac-like closed membranous structure that may be empty or contain fluid or amorphous material. "Treatment with dasatinib led to inhibition of DDR1 tyrosine phosphorylation, slowed cyst growth and preserved renal function in Pkhd1-Cre; Pkd1fl/fl mice when compared with vehicle control treated mice, n = 6 mice/group." (PMID 31260458, 2019). "We therefore also tested genetically if DDR1 played a role in cyst growth in the “slow late” Pax8rtTA; TetO-Cre; Pkd1fl/fl model." (PMID 31260458, 2019). "To explore this possibility further, we analyzed the effect of DDR1 inhibition on cyst formation by MDCK cells in 3D collagen matrices in the absence of HGF." (PMID 30760555, 2019). "In addition, DDR1 is expressed in mouse and human cyst lining epithelia." (PMID 31260458, 2019). "However, the inability of genetically deleting DDR1 to slow cyst growth and preserve renal function in both an “early rapid” and “late slow” mouse model of PKD conclusively demonstrates that DDR1 does not play a role in PKD pathogenesis and thus is not a viable drug target." (PMID 31260458, 2019). "DDR1 was one of many kinases identified in our screen that was more active in PKD kidneys and was localized to cyst lining epithelia." (PMID 31260458, 2019). "However, genetic deletion of DDR1 using CRISPR/Cas9 failed to slow cyst growth or preserve kidney function in both a rapid and slow mouse model of ADPKD demonstrating that DDR1 does not play a role in PKD pathogenesis and is thus a not viable drug target." (PMID 31260458, 2019).
diffuse large B-cell lymphoma (2 papers, 2025). "Furthermore, DDR1 overexpression has been observed in a subset of diffuse large B-cell lymphoma (DLBCL), where its expression positively correlates with that of collagen ligands and negatively correlates with the expression of mitotic spindle genes." (PMID 40713963, 2025). "To address this gap, we aim to investigate DDR1 degraders and identify DDR1-associated DUBs, offering potential new therapeutic strategies for the treatment of non-small cell lung cancer (NSCLC) and diffuse large B-cell lymphoma (DLBCL)." (PMID 40713963, 2025).
dwarfism (2 papers, 2020 to 2022). "Global DDR1 knockout in mice causes dwarfism, and the body weight is more decreased than in wild-type mice." (PMID 33003599, 2020). "However, the mechanism of global Ddr1 knockout that causes dwarfism in mice and whether DDR1 regulates the function of osteoblasts during development remain undefined." (PMID 33003599, 2020). "We have previously shown that DDR1 plays a crucial role during bone development, resulting in dwarfism and a short stature in osteoblast-specific knockout mice (OKO mice)." (PMID 36140274, 2022).